FKRP (fukutin related protein)
Description:
Catalyzes the transfer of a ribitol 5-phosphate from CDP-L-ribitol to the ribitol 5-phosphate previously attached by FKTN/fukutin to the phosphorylated O-mannosyl trisaccharide (N-acetylgalactosamine-beta-3-N-acetylglucosamine-beta-4-(phosphate-6-)mannose), a carbohydrate structure present in alpha-dystroglycan (DAG1). This constitutes the second step in the formation of the ribose 5-phosphate tandem repeat which links the phosphorylated O-mannosyl trisaccharide to the ligand binding moiety composed of repeats of 3-xylosyl-alpha-1,3-glucuronic acid-beta-1.
Synonyms: LGMD2I; MDC1C; FKTR; LGMDR9; MDDGA5; MDDGB5; MDDGC5
Tractability: Small molecule: a structure with a bound ligand is known. Antibody: UniProt places it where antibodies can reach, with high confidence; UniProt predicts a signal peptide or a membrane-spanning region; its Gene Ontology location is reachable by antibodies, with medium confidence. PROTAC: ubiquitination databases record sites on it; its protein half-life has been measured.
Gene: Protein-coding gene on chromosome 19 (46,746,046 to 46,776,988, forward strand). Ensembl gene ENSG00000181027.
Subcellular location: Golgi apparatus membrane; Secreted; Cell membrane, sarcolemma; Rough endoplasmic reticulum; Cytoplasm
Subcellular location (Human Protein Atlas): Cytosol; Golgi apparatus; Nucleoplasm; Predicted to be secreted
Pathways (Reactome):
Metabolism of proteins: Matriglycan biosynthesis on DAG1
Gene Ontology:
Molecular function: identical protein binding; phosphotransferase activity, for other substituted phosphate groups; protein binding
Biological process: protein O-linked glycosylation via mannose; protein tetramerization
Cellular component: catalytic complex; extracellular region; Golgi apparatus; Golgi membrane; rough endoplasmic reticulum; cytoplasm; sarcolemma
Genetic constraint (gnomAD): Loss-of-function variants: 25 observed, 22.6 expected, observed/expected ratio (o/e) 1.11, 90% interval 0.81 to 1.54. The synonymous counts are far from expectation, so gnomAD's model fits this gene poorly and the ratio says little. Missense variants: 771 observed, 603.45 expected, observed/expected ratio (o/e) 1.28, 90% interval 1.2 to 1.36. Synonymous variants: 358 observed, 273.77 expected, observed/expected ratio (o/e) 1.31, 90% interval 1.2 to 1.43.
Gene-disease validity (ClinGen):
ClinGen rates the evidence that FKRP causes each of these diseases.
myopathy caused by variation in FKRP (autosomal recessive): Definitive. Any myopathy in which the cause of the disease is a variation in the FKRP gene.
Homologues: Orthologues: chimpanzee FKRP (99% identical), macaque FKRP (99% identical), dog FKRP (95% identical), pig FKRP (95% identical), rabbit FKRP (95% identical), mouse Fkrp (94% identical), rat Fkrp (93% identical), guinea pig FKRP (93% identical), zebrafish fkrp (60% identical), tropical clawed frog fkrp (53% identical), Drosophila melanogaster CG15651 (25% identical).
Diseases named in the same sentence as FKRP in open-access papers:
FKRP is named in the same sentence as 59 diseases in open-access papers, as found by Europe PMC text mining. Sharing a sentence is not in itself a finding about the gene and the disease. The quoted sentences say what the papers report.
dystroglycanopathies (36 papers, 2011 to 2026). "This study aimed to determine if ribose is well tolerated in a patient with dystroglycanopathy due to an FKRP mutation as well as to study the effect of ribose supplementation on muscle strength and function in this patient." (PMID 38736632, 2024). "This study showed that ribose can be used safely in a dose of both 9 g and 18 g per day during periods of 3 months in a patient with genetically confirmed dystroglycanopathy due to an FKRP mutation." (PMID 38736632, 2024). "As a result, this enhanced laminin binding to dystroglycan, suggesting the potential for ribitol to enhance muscle function in dystroglycanopathy patients with an FKRP mutation." (PMID 38736632, 2024). "LGMD R7 telethonin-related was found in 14.6% (6/41) of index patients, and dystroglycanopathies (including mutations in FKRP, POMT1, POMT2 and ISPD) were found in 12.2% (5/41) of index patients." (PMID 37974208, 2023). "Mutations causing loss of function in FKRP lead to a broad spectrum of dystroglycanopathy-associated symptoms, primarily affecting the development of the muscles and heart, but also the brain and eyes." (PMID 37239976, 2023). "Limb-Girdle Muscular Dystrophy R9 (LGMDR9) is a dystroglycanopathy caused by Fukutin-related protein (FKRP) defects leading to the deficiency of α-DG glycosylation, essential to membrane integrity." (PMID 37887288, 2023). "FKRP-linked disorders have been defined as the most severe forms of dystroglycanopathy and it has been suggested that a full loss of function of this protein results in embryonic lethality." (PMID 37239976, 2023). "Immunoprecipitation combined with SWATH-MS was successfully employed to investigate fukutin-related protein (FKRP)-associated dystroglycanopathy." (PMID 37509144, 2023). "We recently reported that ribitol is able to partially restore matriglycan in the dystroglycanopathy model with mutations in FKRP gene." (PMID 36454905, 2022). "We reported earlier that, ribitol, a natural pentose alcohol delivered by drinking water ad libitum can restore therapeutic levels of matriglycan and ameliorate dystroglycanopathy caused by FKRP P448L mutation associated with severe CMD phenotype in clinic." (PMID 36454905, 2022). "Despite the vast clinical spectrum, all FKRP-associated diseases share a common biochemical defect, hypoglycosylation of α-dystroglycan (α-DG), and therefore are commonly referred to as dystroglycanopathies." (PMID 34260922, 2021). "A requirement for the development of iPS cell-based autologous cell therapy for MDs such as FKRP-associated dystroglycanopathies is the correction of underlying genetic mutations before the generation of myogenic progenitors." (PMID 34260922, 2021). "At present, 18 genes involved in the α-DG glycosylation pathway have been linked to dystroglycanopathies, including the fukutin-related protein (FKRP; OMIM 606596)." (PMID 32321586, 2020). "Fukutin-related protein (FKRP) catalyses the addition of ribitol-phosphate (RboP) to the O-mannosyl glycan of α-dystroglycan and mutations in FKRP cause dystroglycanopathy." (PMID 31949166, 2020). "Fukutin and fukutin-related protein (FKRP), whose mutated genes underlie dystroglycanopathy, sequentially transfer RboP from cytidine diphosphate-ribitol (CDP-Rbo) to form a tandem RboP unit in the core M3 glycan." (PMID 31949166, 2020). "In this study, we demonstrated a molecular mechanism connecting dystroglycanopathy with a deficiency of the oligomerization of FKRP." (PMID 31949166, 2020). "Another candidate experimental therapy – overexpression of the LARGE enzyme – has been shown to restore αDG function in a variety of α-dystroglycanopathies caused by mutations in FKRP, FKTN, POMGNT1 and POMT1." (PMID 32423971, 2020). "FKRP mutations are associated with a large spectrum of dystroglycanopathies from severe forms, such as congenital muscular dystrophy and Walker–Warburg syndrome, to limb girdle muscular dystrophy type 2I (LGMD2I)." (PMID 32321586, 2020).
dystroglycanopathies (continued). "Among these mutations, the FKRP c.826C>A (L276I) mutation is the most common variant and causes a mild form of dystroglycanopathy (LGMD2I), which is among the most common LGMD forms especially in the Caucasian population." (PMID 31566294, 2019). "Patients with FKRP-associated dystroglycanopathy present with phenotypic variability; however, muscle weakness and elevated serum creatine kinase are consistently present." (PMID 31391079, 2019). "FKRP-associated dystroglycanopathy results from mutations in FKRP, which encodes an enzyme critical for DG glycosylation." (PMID 31391079, 2019). "Gene therapy, estrogen receptor modulators, and exogenous ribitol supplementation improve muscle structure in FKRP-associated dystroglycanopathy models." (PMID 31391079, 2019). "Here, we generated induced pluripotent stem cells (iPSCs) from a severe dystroglycanopathy patient with homozygous FKRP (fukutin‐related protein gene) mutation." (PMID 31566294, 2019). "Muscle MRI at the thigh level potentially allows distinction of sarcoglycanopathies or FKRP-associated dystroglycanopathy from dystrophinopathies." (PMID 31747956, 2019). "In conclusion, a distinctive pattern of muscle involvement, the concentric fatty infiltration pattern around the distal femoral diaphysis, is shared by the different sarcoglycanopathies and FKRP-associated dystroglycanopathy." (PMID 31747956, 2019). "Zebrafish models of FKRP-associated dystroglycanopathy are also associated with endoplasmic reticulum (ER) stress and activation of the unfolded protein response (UPR)." (PMID 31391079, 2019). "Our genome‐editing strategy can be applied to precisely correct these FKRP missense mutations and by implication small insertion/deletion mutations (INDELs), as well as similar type of mutations in other dystroglycanopathy genes." (PMID 31566294, 2019). "Mouse and zebrafish models of FKRP deficiency have been used to study mechanisms associated with FKRP-associated dystroglycanopathy." (PMID 31391079, 2019). "FKRP is a gene that encodes fukutin-related protein and its mutations cause dystroglycanopathies of both LGMD and CMD phenotypes as well as muscle-eye-brain and Walker-Warburg syndrome." (PMID 29625576, 2018). "Fukutin-related protein (FKRP) mutations are the most common cause of dystroglycanopathies known to cause both limb girdle and congenital muscular dystrophy." (PMID 29625576, 2018). "Mutations in the gene for fukutin-related protein represent a subset of muscular dystrophies known as dystroglycanopathies characterized by loss of functionally-glycosylated-alpha-dystroglycan and a wide range of dystrophic phenotypes." (PMID 27711214, 2016). "Mutations in the gene encoding fukutin-related protein (FKRP) are one of the most common causes of secondary dystroglycanopathy in the UK and are associated with a wide spectrum of disease." (PMID 26900448, 2016). "Mutations in the FKRP gene are a common cause of dystroglycanopathies." (PMID 40833945, 2025). "Mutations in the FKRP gene are among the most common causes of dystroglycanopathy." (PMID 40833945, 2025). "Therefore, future research in a larger cohort is needed to elucidate the potentially beneficial effects of this supplement in dystroglycanopathy patients with an FKRP, FKTN, or ISPD mutation." (PMID 38736632, 2024). "(d) Several subtypes of LGMDs are dystroglycanopathies, primarily caused by mutations in eight genes, including FKRP (R9), POMT1 (R11), FKTN (R13), POMT2 (R14), POMGnT1 (R15), GMPPB (R19), ISPD (R20), and POMGNT2 (R24), involved in the glycosylation of the alpha-dystroglycan pathway." (PMID 37974208, 2023). "Finally, this study opens a path to a better understanding of the mutated FKRP causing dystroglycanopathies and should contribute to the future development of therapeutic strategies." (PMID 31949166, 2020).
dystroglycanopathies (continued). "The distinctive patterns observed at the thigh level of DGC-related muscular dystrophies, including the trefoil with single fruit sign and concentric fatty infiltration pattern, are highly specific for dystrophinopathies and FKRP-associated dystroglycanopathy, respectively." (PMID 31747956, 2019). "Together, our results demonstrated that target gene mutation of FKRP by CRISPR/Cas9‐mediated genome editing could recapitulate pathological hallmarks of dystroglycanopathy in human iPSC‐derived cortical neurons." (PMID 31566294, 2019). "One most common dystroglycanopathy caused by mutations in the fukutin-related protein (FKRP) gene manifests a wide range of disease severity from mild limb girdle muscular dystrophy (LGMD) 2I to severe congenital muscular dystrophy (CMD), Walker–Warburg syndrome, and muscle–eye–brain disease." (PMID 30150693, 2018). "FKRP mutations are the most common causes of the dystroglycanopathies." (PMID 27711214, 2016). "Mutations in ISPD, FKTN and FKRP lead to dystroglycanopathies with severe neuromuscular symptoms." (PMID 27194101, 2016). "However some predictions are hard to interpret, for example, the similarity of hereditary spastic paraplegia caused by mutation in SPG4 gene and dystroglycanopathy caused by mutation in FKRP protein, involved in glycosylation of dystroglycan." (PMID 24416320, 2014). "Indeed, in vivo study in dystroglycanopathy mouse model with FKRP mutations confirms that ribitol treatment is able to increase the levels of CDP-ribitol and partially restore the hypoglycosylation of α-DG in both skeletal and cardiac muscles with improvement in muscle functions." (PMID 39779805, 2025). "Recently, dietary supplementation with ribitol was shown to improve muscle phenotypes in a mouse model of FKRP-related α-dystroglycanopathy." (PMID 32423971, 2020). "Here, we generated the first human FKRP‐iPSCs from a dystroglycanopathy patient with severe CNS abnormalities." (PMID 31566294, 2019). "We used the fkrp morphant model of FKRP-associated dystroglycanopathy to address unanswered questions regarding NAD+ regulation of the ECM in a secondary dystroglycanopathy." (PMID 31391079, 2019). "In this study, we have developed a novel isogenic, human FKRP‐iPSC‐based platform for modeling dystroglycanopathy and testing potential drug candidates." (PMID 31566294, 2019). "LGMD2I is a dystroglycanopathy, caused by homozygous or compound heterozygous mutation in the FKRP gene (fukutin-related protein)." (PMID 30524939, 2018). "We consider the P448Lneo− mouse highly relevant and valuable for developing experimental therapies to FKRP dystroglycanopathy." (PMID 29625576, 2018). "Similar results have previously been reported in dystroglycanopathy patients with Protein-O-mannosyl transferase 1 (POMT1), Protein-O-mannosyl transferase 2 (POMT2), POMGnT1, FKTN and FKRP mutations." (PMID 30553274, 2018). "Here, we show that muscle phenotypes in a zebrafish model of FKRP-associated dystroglycanopathy are improved with NAD+ supplementation but not Paxillin overexpression." (PMID 31391079, 2019). "Taken together, these data indicate that, at least in the zebrafish, FKRP-associated dystroglycanopathy does not phenocopy DG-deficiency." (PMID 31391079, 2019). "Despite significant advances in understanding the causes and clinical manifestation of dystroglycanopathies, almost no progress has been made for the treatment of the diseases including those caused by FKRP mutations." (PMID 30150693, 2018). "To date, at least 18 genes, including fukutin, fukutin-related protein (FKRP), isoprenoid synthase domain-containing protein (ISPD), and like-acetylglucosaminyltransferase (LARGE), have been identified as causative genes for dystroglycanopathy." (PMID 29360985, 2018). "Phenotypic variability is not unique for mutations in the FKRP gene, and a similar spectrum of clinical involvement has been observed for most of the other dystroglycanopathy genes." (PMID 26900448, 2016).
dystroglycanopathies (continued). "However, no causative treatment is yet available for ISPD, FKTN, and FKRP‐related dystroglycanopathies." (PMID 38736632, 2024). "There is no effective treatment for FKRP-associated dystroglycanopathies." (PMID 34260922, 2021). "Other genes contributing to dystroglycanopathies through glycosylation errors include POMT1, POMT2, POMGNT1, FKRP, ISPD and LARGE1." (PMID 38439105, 2024). "We tested endoderm-free embryoid bodies from control subjects and LARGE, FKRP and POMT2 α-dystroglycanopathy patients for their capacity to accumulate laminin." (PMID 32423971, 2020).
muscular dystrophies (33 papers, 2007 to 2025). "The use of orally administered ribose over a six-month period in a patient with muscular dystrophy caused by a mutation in the FKRP gene led to a significant reduction in CPK levels, reduced fatigue and pain, and improved muscle strength." (PMID 41425985, 2025). "The mildest and most common form of muscular dystrophy involving FKRP, LGMDR9, is frequently associated with the mutation, c.826C>A (p.L276I)." (PMID 38161385, 2023). "Limb Girdle Muscular Dystrophy 2I (LGMDR9) is one of the most common LGMD characterized by defects in glycosylation of α-dystroglycan (matriglycan) resulting from mutations of Fukutin-related protein (FKRP)." (PMID 36454905, 2022). "Mutations in the fukutin-related protein (FKRP) gene result in a broad spectrum of muscular dystrophy (MD) phenotypes, including the severe Walker-Warburg syndrome (WWS)." (PMID 34260922, 2021). "Mutations in FKRP lead to a large spectrum of muscular dystrophies, including limb girdle muscular dystrophy 2I (LGMD2I)." (PMID 32321586, 2020). "For individual genes, the prevalence of rare variants was nominally increased only in FKRP (encoding fukutin-related protein); recessive FKRP mutations cause several forms of muscular dystrophies with cardiac involvement." (PMID 30987448, 2019). "Here, the authors show that oral administration of ribitol increases dystropglycan glycosylation and ameliorates symptoms of muscular dystrophy in FKRP-deficient mouse models." (PMID 30150693, 2018). "The results provide new data on outcome measures for future preclinical drug trials using the P448Lneo− mouse as a model system for FKRP deficiency muscular dystrophy." (PMID 29625576, 2018). "There is a marked variation in clinical phenotypes that have been associated with mutations in FKRP, ranging from severe congenital muscular dystrophies to limb-girdle muscular dystrophy type 2I (LGMD2I)." (PMID 18036232, 2007). "The discovery that reducing agents can improve protein folding and enhance intracellular transport of different variants may have a therapeutic potential for treating FKRP-deficient muscular dystrophies." (PMID 38161385, 2023). "It is therefore tempting to speculate that compounds that assist the folding of disease-associated variants could be used to treat FKRP-deficient muscular dystrophies." (PMID 38161385, 2023). "The overwhelming majority of FKRP-related muscular dystrophy are LGMDR9 with mutations such as the common L276I mutation retaining considerably higher function as indicated by residual amounts of matriglycan and milder disease phenotypes when compared to P448L mutant." (PMID 36454905, 2022). "FKRP mutations cause muscular dystrophies with varied clinical presentations." (PMID 34012031, 2021). "Mutations in FKRP impair glycosylation of alpha-dystroglycan, leading to muscular dystrophy." (PMID 30150693, 2018). "Fukutin-related protein (FKRP, MIM ID 606596) variants cause a range of muscular dystrophies associated with hypo-glycosylation of the matrix receptor, α-dystroglycan." (PMID 38161385, 2023). "In particular, the findings point towards NAD+, ribose and ribitol as candidates for treating FKRP-related muscular dystrophies." (PMID 33513091, 2021). "To our knowledge, we are the first to demonstrate the phenotypic correction of FKRP-related muscular dystrophies at multiple stages of disease progression in a mouse model by a single intravenous administration of an AAV vector." (PMID 28480302, 2017). "This is especially important because FKRP-related muscular dystrophies exhibit a wide spectrum of clinical severity, variability in age at onset, and varying degrees of myogenic atrophy." (PMID 28480302, 2017). "In fact, one major obstacle for FKRP-related muscular dystrophies has been the inability to detect endogenous FKRP protein despite great efforts." (PMID 28480302, 2017).